ENSG00000238371
Synonyms: LOC124906147
Gene: Small nucleolar RNA gene on chromosome 2 (15,903,669 to 15,903,772, forward strand). Ensembl gene ENSG00000238371.
Gene Ontology:
Biological process: RNA processing
Cellular component: nucleolus
Homologues: Paralogues in human: SNORD13P3 (81% identical), SNORD13D (80% identical), SNORD13 (79% identical), SNORD13P1 (79% identical), SNORD13E (76% identical).